MSTN (myostatin)
Diseases named in the same sentence as MSTN in open-access papers (continued):
Sharing a sentence is not in itself a finding about the gene and the disease.
liver cirrhosis (14 papers, 2017 to 2025). "On the other hand, elevated serum myostatin levels have been associated with poor prognosis in patients with liver cirrhosis, where increased collagen synthesis is driven by high myostatin levels." (PMID 39594505, 2024). "The role of myostatin on osteosarcopenia in alcoholic patients and/or patients with liver cirrhosis of different causes has been extensively studied, but there is discrepancy in the reported results." (PMID 36769301, 2023). "Negative association between hs-CRP and myostatin level was observed in 355 liver cirrhosis patients like the present results." (PMID 34299795, 2021). "Interestingly, patients with liver cirrhosis displayed a trend (p = 0.081) towards higher Myostatin serum concentrations in comparison to patients with other etiology of critical illness." (PMID 32784522, 2020). "Given that the major etiology of liver cirrhosis in western countries is alcoholic, it might be important to clarify prognostic performance of serum myostatin for clinical outcomes in patients with alcoholic cirrhosis." (PMID 33198216, 2020). "Leading to muscle depletion, sarcopenia in liver cirrhosis is affected by DRM, alterations in protein turnover, energy disposal, hormonal and metabolic changes, increased myostatin expression, reactive oxygen species and inflammatory cytokines." (PMID 32731496, 2020). "In liver cirrhosis, decreased levels of testosterone and IGF-1 contribute to increased myostatin expression and impaired protein synthesis." (PMID 32731496, 2020). "Obese alcoholic patients showed higher myostatin levels, a result that does not depend on the presence of liver cirrhosis or age." (PMID 36769301, 2023).
rheumatoid arthritis (14 papers, 2018 to 2025). A chronic, systemic autoimmune disorder characterized by inflammation in the synovial membranes and articular surfaces. "In patients with rheumatoid arthritis, high myostatin levels indicated the risk of faster disease progression." (PMID 38672190, 2024). "In a mouse model for rheumatoid arthritis, MSTN is highly expressed in synovial tissues, and transgenic or antibody inhibition of MSTN ameliorates joint destruction and arthritis severity." (PMID 39340593, 2025). "In rheumatoid arthritis, elevated myostatin levels positively correlate with disease activity and inflammatory markers while negatively correlating with muscle mass." (PMID 40427596, 2025). "To have a more complete view of the current state of knowledge of serum myostatin levels in rheumatoid arthritis patients, and to identify specific gaps in the knowledge concerning this area, we conducted this review of the current literature." (PMID 38893612, 2024). "In another research on rheumatoid arthritis in remission, serum myostatin was found to decrease in comparison to heathy controls." (PMID 32796600, 2020). "This study shows a possible crucial role of myostatin in the pathogenesis of rheumatoid arthritis, and sets a ground for further investigations on the matter of possible myostatin-target therapies of the disorder mentioned." (PMID 32796600, 2020). "The study went further to demonstrate that inflammatory cytokines such as interleukin 1 (IL-1), interleukin 17 (IL-17) and tumor necrosis factor alpha (TNF-α) expressed during rheumatoid arthritis leads to increases in myostatin expression which in turns enhances osteoclast differentiation." (PMID 36151243, 2022). "Importantly, myostatin is highly expressed in the synovial tissues of rheumatoid arthritis (RA) subjects, and the inhibition of its activity can prevent bone destruction by regulating osteoclastogenesis." (PMID 29247983, 2018). "Studies in mice show that inhibition of the myokine myostatin pathway leads to an increase in bone mass, whereas myostatin reduces osteoclast formation and bone destruction in a TNF-α transgenic mouse model of rheumatoid arthritis." (PMID 32393961, 2020). "According to our study, myostatin inhibition could result in lower FGF23, which may indeed be beneficial with regard to the reduced bone mass typical of both Duchenne muscular atrophy and rheumatoid arthritis." (PMID 33895875, 2021).
type 1 diabetes (14 papers, 2015 to 2025). "Increased serum myostatin levels are associated with type 1 diabetes and insulin secretion deficiency." (PMID 39562792, 2024). "Evidence in rodent models suggests that myostatin expression is elevated in type 1 diabetes (Chen, Cao, Ye, & Zhu, 2009) and elevated myostatin expression is associated with impaired insulin signaling/sensitivity." (PMID 32652899, 2020). "shown that serum myostatin levels were significantly higher in type 1 diabetes (T1D) patients than in the control group and were higher in T1D women than in T1D men." (PMID 37288303, 2023). "Here, we report for the first time, the myostatin expression levels in the blood and muscle of persons with type 1 diabetes." (PMID 32652899, 2020). "Additionally, insulin injection has been demonstrated to suppress the expression of myostatin in type 1 diabetic rats." (PMID 37576807, 2023). "Pharmacologic myostatin inhibition could be a potential future target to improve deficits in muscle and bone in those with type 1 diabetes." (PMID 38025035, 2023). "Similarly, LIPUS significantly inhibited MSTN expression in type 1 diabetic rats, exercise-induced muscle hypertrophy rats and ovariectomized rats." (PMID 34829990, 2021). "In women with type 1 diabetes, serum myostatin was significantly higher relative to control women." (PMID 32652899, 2020). "Myostatin, a negative regulator of muscle size/health is increased in type 1 diabetes." (PMID 32652899, 2020). "Thus, the purpose of the current study was to investigate the expression of myostatin in men and women with type 1 diabetes and, secondarily, explore relationships between myostatin expression and clinically important health metrics." (PMID 32652899, 2020). "There was also a notably elevated serum myostatin expression in men with type 1 diabetes versus controls (~33%) though this difference did not meet statistical significance (p = 0.08)." (PMID 32652899, 2020). "Despite accumulating evidence for a role of myostatin in the maintenance of skeletal muscle function and metabolic health, its expression in the blood and muscle of those with type 1 diabetes has not previously been reported." (PMID 32652899, 2020).
Sepsis (13 papers, 2017 to 2025). Sepsis is defined as life-threatening organ dysfunction caused by a dysregulated host response to infection. "Is there an association between Myostatin levels and the severity of organ dysfunction or the presence of sepsis (secondary objective)?" (PMID 32784522, 2020). "Therefore, after sepsis induction, myostatin was consumed in the muscle, which caused the decrease of the serum myostatin level." (PMID 40939142, 2025). "Our aim was to investigate Myostatin levels as a potential prognostic biomarker in critically ill patients with sepsis." (PMID 32784522, 2020). "Serum concentrations of Myostatin can predict poor survival in different chronic diseases, but its role in critical illness and sepsis is obscure." (PMID 32784522, 2020). "In septic mice, knocking out the myostatin gene prevents sepsis‐induced muscle atrophy." (PMID 40939142, 2025). "The myostatin inhibitor YK11 has preventive effects against sepsis‐induced muscle atrophy." (PMID 40939142, 2025). "Our data suggest that myostatin is a regulator of locomotor muscle mass during sepsis." (PMID 28883493, 2017). "Therefore, the pharmacological inhibition of myostatin can prevent sepsis‐induced muscle atrophy." (PMID 40939142, 2025). "Circulating serum myostatin levels are upregulated in response to inflammatory cytokines in diseases such as AIDS, cancer, and sepsis." (PMID 34368273, 2021). "However, the sepsis‐induced upregulation of atrophy markers (Fbxo32, Trim63, Ubc, Ubb) was further increased in the Low‐LCT and High‐LCT groups, while expression of myostatin (Mstn) was higher only in the Low‐LCT group." (PMID 41365288, 2025). "For instance, mice with sepsis showed increased myostatin protein levels with decreased myostatin mRNA levels (rather than increased)." (PMID 38673892, 2024). "Even if Myostatin was not able to indicate presence of sepsis, it correlated with deterioration of organ function since patients depending on mechanical ventilation and intravenous vasopressors showed lower Myostatin levels." (PMID 32784522, 2020). "In contrast, several studies have suggested that myostatin expression in skeletal muscle is not increased in sepsis models." (PMID 28742154, 2017). "Whereas, myostatin transcript level was transitory increased by about 3-fold in gastrocnemius muscle one day after CLP, myostatin mRNA level remained unchanged in diaphragm muscle, suggesting that this differential response may contribute to preserve the mass of diaphragm muscle during sepsis." (PMID 28883493, 2017).
Hyperglycemia (12 papers, 2011 to 2025). An increased concentration of glucose in the blood. "MSTN signaling also affects glucose metabolism, with Mstn−/− mice able to maintain normal or lower fasting glucose levels despite having lower insulin levels and loss of MSTN capable of partially suppressing the development of hyperglycemia and enhancing glucose clearance in genetically obese mice." (PMID 36266260, 2023). "This is a new mechanism, linking hyperglycemia and MSTN in the pathogenesis of diabetic nephropathy." (PMID 32286342, 2020). "We showed that both high glucose and glycated albumin caused an overexpression of MSTN and its receptor in human proximal tubular cells, suggesting that the hyperglycemic milieu per se or downward signals produced by hyperglycemia induce tubular MSTN." (PMID 32286342, 2020). "Skeletal muscle may attempt to counteract muscular atrophy and hyperglycemia by decreasing intramuscular myostatin." (PMID 39590324, 2024).
malnutrition (12 papers, 2020 to 2025). Inadequate nutrition resulting from poor diet, malabsorption, or abnormal nutrient distribution. "We found that the risk of malnutrition increased by 0.001-fold for every 1 pg/ml increase in MSTN, indicating that muscle growth was more significantly inhibited in the malnutrition group." (PMID 40813643, 2025). "They recognized malnutrition in females and higher serum myostatin in males as different risk factors for sex-specific difference of muscle aging in humans." (PMID 35017317, 2022). "By influencing myostatin, FSTL-1 plays a crucial role in muscle growth and maintenance, especially under conditions of energy deficiency or malnutrition." (PMID 40077702, 2025). "The ROC analysis identified albumin, leptin, myostatin, and adiponectin as biomarkers of malnutrition diagnosed using the 7-Point SGA." (PMID 39125361, 2024). "Physical performance or strength in HD patients can be influenced by many factors, such as aging, malnutrition, myostatin, uremic toxins, volume status, and inflammation." (PMID 37095121, 2023). "Furthermore, the proposed inflammation-GHRL/MSTN-appetite improvement/muscle growth-CHF improvement pathway offers a potential regulatory mechanism,which represents a promising direction for research into the mechanisms of malnutrition and muscle loss disorders in patients with CHF." (PMID 40813643, 2025). "In this study, MSTN levels were higher in the CHF with malnutrition compared to those without malnutrition." (PMID 40813643, 2025). "Additionally, this study will compare the correlations between GHRL, MSTN, C-reactive protein (CRP), and high-sensitivity C-reactive protein (Hs-CRP), to further elucidate the potential relationship between malnutrition/muscle wasting disease and inflammatory pathophysiological mechanisms." (PMID 40813643, 2025).
spinal muscular atrophy (12 papers, 2009 to 2025). A motor neuron disease that affect the muscles, and characterized by muscle weakness and atrophy resulting from progressive degeneration and irreversible loss of the anterior horn cells in the spinal cord (i.e., lower motor neurons) and the brain stem nuclei. "It is worth noting that neurogenic muscle atrophy caused by amyotrophic lateral sclerosis and spinal muscular atrophy may be ameliorated by myostatin inhibition either by myostatin antibody or follistatin." (PMID 19538713, 2009). "This review synthesizes findings from both preclinical and clinical studies investigating myostatin modulation in Spinal Muscular Atrophy." (PMID 40565321, 2025). "A systematic search was conducted on PubMed using the following search criteria “spinal muscular atrophy” AND (myostatin OR “growth differentiation factor 8”)." (PMID 40565321, 2025). "Serum myostatin levels show promise as a novel biomarker for evaluating the severity and progression of spinal muscular atrophy." (PMID 38487549, 2024). "This study aimed to investigate the role of serum levels of myostatin and follistatin as biomarkers for spinal muscular atrophy, considering muscle atrophy secondary to denervation as the main clinical manifestation of the disease." (PMID 38487549, 2024). "Clinical trials with treatments inhibiting myostatin pathways to increase muscle mass are currently ongoing in spinal muscular atrophy." (PMID 39201450, 2024). "After 12 months, there was a further reduction in myostatin levels among spinal muscular atrophy cases (P = 0.021)." (PMID 38487549, 2024). "Median serum myostatin levels were significantly lower in spinal muscular atrophy patients (98 pg/mL; 5–157) compared to controls (412 pg/mL; 299–730) (P < 0.001)." (PMID 38487549, 2024). "The follistatin:myostatin ratio was significantly increased in spinal muscular atrophy subjects and inversely correlated with motor severity." (PMID 38487549, 2024). "Regarding the low expression level of myostatin, the study showed a two-fold or higher decrease in circulating myostatin in the most atrophic disease, spinal muscular atrophy (SMA), and the most wasting disease, DMD." (PMID 36012334, 2022). "Skeletal muscle gene expression of myostatin decreased and of follistatin increased following lesional muscle denervation in mice, consistent with findings in the spinal muscular atrophy transgenic mice meta-analysis and in the iliopsoas muscle of five patients with spinal muscular atrophy type 1." (PMID 38487549, 2024). "Furthermore, delivery of recombinant follistatin, a natural antagonist of myostatin, in a mouse model of spinal muscular atrophy, has been shown to increase the number and size of ventral horn cells together with the gross motor function of mice." (PMID 29070788, 2017). "Given evidence of potential myostatin pathway downregulation in Spinal Muscular Atrophy (SMA), restoring sufficient myostatin levels using disease-modifying treatments (DMTs) might arguably be necessary prior to considering myostatin inhibitors as an add-on treatment." (PMID 39201450, 2024).
Hepatic steatosis (11 papers, 2011 to 2024). Steatosis is a term used to denote lipid accumulation within hepatocytes. "Further, a constitutive MSTN loss-of-function mutation also attenuates fat accumulation in muscle tissue and hepatic steatosis in mice fed a high-fat diet." (PMID 25859286, 2014). "A constitutive myostatin gene mutation also attenuated the hepatic steatosis induced by a high-fat diet." (PMID 21390326, 2011). "A constitutive myostatin gene mutation attenuated the hepatic steatosis induced by a high-fat diet." (PMID 21390326, 2011). "Thus, BAT-specific MSTN deficiency aggravated hepatic steatosis." (PMID 38889010, 2024). "Muscle-specific deletion of the myostatin (myostatinMSD) gene prevents hepatic steatosis with high-fat diet (HFD) in mice." (PMID 38323119, 2024). "One myostatin secreted by skeletal muscle as an endocrine organ plays arole not only in regulating skeletal muscle mass and metabolism but also in liversteatosis." (PMID 38451586, 2024). "Here, we reported that AAV-mediated delivery of a myostatin pro-peptide D76A mutant in adult mice attenuates the development of hepatic steatosis and arteriosclerosis, two common diet-induced metabolic diseases." (PMID 23936482, 2013). "Blocking myostatin in mice with a soluble activin receptor type IIB reduced hepatic steatosis induced by androgen deprivation." (PMID 21390326, 2011). "The studies cited above raise the possibility that an anti-myostatin therapy, if one can be developed, would reduce fat mass, glucose levels, and hepatic steatosis in obese humans." (PMID 21390326, 2011). "Myostatin depletion also attenuated hepatic steatosis and accumulation of fat in muscle tissue." (PMID 21390326, 2011). "In the present study, we used a genetic approach to specifically eliminate myostatin activity after normal development, and we examined how this affected weight gain, muscle mass, fat mass, glucose levels and hepatic steatosis after a prolonged period of high-fat feeding." (PMID 21390326, 2011). "•Beige fat is not required for the protection from hepatic steatosis in myostatin null mice." (PMID 33220490, 2021).
Arthritis (10 papers, 2012 to 2025). Inflammation of a joint. "Deficiency of MSTN or its neutralisation reduces the severity of arthritis in hTNFtg mice, primarily through a decrease in bone resorption." (PMID 38001998, 2023). "In this study, we used myostatin-deficient arthritic (Mstn−/− hTNFtg) mice to investigate the role of myostatin in regulating inflammation during arthritis development." (PMID 34239010, 2021). "Our group has reported that chronic arthritis decreases Pparα expression in liver and gastrocnemius, whereas the PPARα agonist fenofibrate improves arthritis-induced body weight loss and gastrocnemius muscle wasting by decreasing atrogenes and myostatin." (PMID 23781298, 2012). "In addition, fenofibrate reverts arthritis-induced decrease in soleus mass and this effect is associated with decreased expression of Murf1 and myostatin, as well as upregulation of MyoD and myogenin expressions." (PMID 23781298, 2012). "A recent animal study found that the increased expressions of certain genes in muscle atrophy (MSTN, atrogin-1, MyoD, and myogenin) in mice with experimental arthritis are restored back to control levels following acute resistance exercise." (PMID 38001998, 2023). "In experimental studies of induced arthritis, myostatin regulates the recruitment of Th17 cells through increased levels of CCL20 on joint tissues, which subsequently induces an increase in IL-17 levels, contributing to the persistence of inflammation." (PMID 35592686, 2022). "Surprisingly, the skeletal muscle regulatory protein myostatin (MSTN) was identified as a novel downstream mediator that links IFNβ to severe arthritis in response to B. burgdorferi infection." (PMID 35324997, 2022). "Blockade of the CCL20–CCR6 axis by inhibition of myostatin may, therefore, be a promising treatment option for chronic inflammatory diseases such as arthritis." (PMID 34239010, 2021). "Quantitative histomorphometric analysis showed considerably less joint inflammation by about 50% in hind paws and about 70% in knees of Mstn−/− hTNFtg compared to hTNFtg mice, substantiating an important regulatory role of myostatin in inflammation in arthritis." (PMID 34239010, 2021). "Based on these findings, the aim of this study was to elucidate whether FLS-derived myostatin is involved in the recruitment of immune cells to the inflamed tissues thereby contributing to the persistence of joint inflammation in a chronic TNF-a-mediated arthritis mouse model." (PMID 34239010, 2021). "Myostatin mRNA and protein content were not modified by arthritis." (PMID 23781298, 2012).